YAP1 (Yes1 associated transcriptional regulator)
Diseases named in the same sentence as YAP1 in open-access papers (continued):
Sharing a sentence is not in itself a finding about the gene and the disease.
breast cancer (continued). "Western blotting showed that ERK1 knockdown increased the protein expression of YAP1 and phosphorylated YAP1 in luminal breast cancer cells, especially in MCF7 cells with higher ERK1 protein level." (PMID 31848326, 2019). "In particular, the most recent studies have indicated that YAP1 and its target genes were overexpressed in basal breast cancer subtype and pivotal for maintaining cancer cell stemness and drug resistance." (PMID 31848326, 2019). "Our results supported a tumor suppressor role of ERK1 in breast cancer via suppression of YAP1 signaling pathway." (PMID 31848326, 2019). "The gene set enrichment analysis (GSEA) further showed enrichment for YAP1 signaling pathway in breast cancer cell lines and tumors with low expression of ERK1." (PMID 31848326, 2019). "Our following experiments confirmed that ERK1 negatively regulated YAP1 at mRNA level in breast cancer cells." (PMID 31848326, 2019). "In this article, the specific roles of ERK1 and ERK2 in regulation of YAP1 signaling in breast cancer were studied." (PMID 31848326, 2019). "The nuclear translocation of YAP1 and TAZ is associated with increased breast cancer progression, metastasis, epithelial-to-mesenchymal transition (EMT), epithelial stem cell regeneration, and therapeutic resistance." (PMID 30042827, 2018). "Upregulated miR-200a enhances treatment resistance via antagonizing TP53INP1 and YAP1 in breast cancer." (PMID 29329575, 2018). "In luminal A breast cancer samples, YAP1 expression levels negatively correlates with Estrogen positive (ER+) samples, and positively correlates with proliferation in ER- samples." (PMID 30619734, 2018). "In breast cancer, deregulation of Hippo signaling can drive progression through the activation of its effector molecules YAP1 (Yes-associated protein 1) and TAZ (transcriptional co-activator with PDZ binding motif)." (PMID 30042827, 2018). "We identified four genes that were overexpressed in cluster 2 cells—KRT7, NOTCH3, CD146, and YAP1—and analyzed publicly available expression data to assess the relevance of these genes in breast cancer." (PMID 29606612, 2018). "Compared with ER positive breast cancer cells and normal cells, YAP1 expression was predominantly observed in the nucleus and at higher levels in TNBC cells." (PMID 29228705, 2017). "Here we show that yes-associated protein 1 (YAP1), a transcriptional regulator that controls tissue growth and regeneration, has an important role in tumor necrosis factor α (TNF α)-induced breast cancer migration." (PMID 28945218, 2017). "We also analyzed the expression of ANKRD1 and YAP1 in different human cancer cell lines, including lung cancer (H322, A549 and A427), prostate cancer (LNCaP and PC-3), breast cancer (MCF7) and skin cancer (MeWo and Sk-Mel-28)." (PMID 29179447, 2017). "We analyzed total and phosphorylated (p) YAP1 protein expression in a panel of human breast cancer cell lines that included ER (+), TNBC and normal cells." (PMID 29228705, 2017). "Statins, which are 3-hydroxy-methylglutaryl CoA reductase inhibitors generally used as cholesterol-lowering drugs, are also reported to inhibit the activity of YAP1 in breast cancer." (PMID 29212185, 2017). "As a result, Yap1 status was an independent poor prognosis factor of mOS in breast cancer that was consistent with the 15-year survival rate (7.8 yr." (PMID 26695440, 2016). "We have identified that over-expression of BAG3, YAP1 and LGALS1 was associated with poor prognosis in HER2-positive breast cancers." (PMID 26883193, 2016). "Previous research indicated that Yap1 was a potent oncogene that promotes breast cancer cells to metastasize in vivo to and proliferate in stiff surfaces in vitro." (PMID 26695440, 2016).
breast cancer (continued). "All of these studies suggest that Yap1 functions in breast cancer initiation and treatment sensitivity are complex." (PMID 26695440, 2016). "We further demonstrate that our data are consistent with the survival data from human breast cancer patients, showing that elevated Yap1 expression is correlated with a poor survival outcome, especially for basal-type breast cancers." (PMID 26695440, 2016). "Our data suggest that, in breast cancer cells, YAP1/β-catenin complex with TBX3, which phenocopies TBX5 at BCL2L1 and BIRC5 but additionally promotes cMYC expression, potentially by combining known TEAD- and TBX3-binding elements." (PMID 26549256, 2015). "The up-regulation and nuclear localization of YAP1 has been shown to correlate with progression, metastasis and poor patient outcome in several cancers, such as non small cell lung cancer, breast cancer, gastric carcinoma and hepatocellular carcinoma." (PMID 25473897, 2015). "In this study, we have examined the expression of YAP1 both on protein and gene expression level in a total of 1751 primary breast cancer samples with clinical follow-up." (PMID 24559095, 2014). "Despite these reports pointing to YAP1 as an oncogene, the role of YAP1 in breast cancer is far from clear." (PMID 24559095, 2014). "The normal cell line subsequently used for transformation experiments was MCF-10A, reported to be ER-, altogether suggesting a possible function of YAP1 as an oncogene in ER- breast cancer." (PMID 24559095, 2014). "The fundamental differences on the transcriptomic level of ER+ and ER- breast cancers is long established, and our results indicate that subgroup analysis is critical for the translational understanding of YAP1 in breast disease." (PMID 24559095, 2014). "In this study, we have shown that decreased mRNA levels of YAP1 independently predict outcome in ER+ and more specifically, luminal A breast cancers." (PMID 24559095, 2014). "YAP1 mRNA expression was also explored using a large gene expression dataset consisting of six previously published primary breast cancer datasets totalling 1107 patients." (PMID 24559095, 2014). "In ER- breast cancer the relationship is opposite and increased YAP1 expression correlated to increased proliferation." (PMID 24559095, 2014). "Similar results were obtained upon depletion of YAP1 in the basal-like SW527 human breast cancer cell line, altogether suggesting YAP1 to function as an oncogene in breast cancer." (PMID 24559095, 2014). "We suggest this result relates to a decrease in tamoxifen sensitivity which potentially results from the altered levels of estrogen receptor (ER) and progesterone receptor (PgR) observed upon YAP1 downregulation in the luminal breast cancer cell line T47D." (PMID 24559095, 2014). "To date, there are several reports on the function of YAP1 as an oncogene in breast cancer models, but tumour suppressive functions have also been reported." (PMID 24559095, 2014). "Activation of YAP1 in the ER- cell line SUM159 mediated by LIFR (leukemia inhibitory factor receptor) repression resulted in substantial lung metastases in nude mice, again suggesting an oncogenic role of YAP1 in ER- breast cancer." (PMID 24559095, 2014). "KLF5 and YAP1 were reported to be predominately expressed in ER- cell lines and all experimental data was obtained from ER- breast cancer cell lines." (PMID 24559095, 2014). "Decreased YAP1 expression is an independent prognostic factor for recurrence in the less aggressive luminal A breast cancer subgroup, likely due to the decreased tamoxifen sensitivity conferred by YAP1 downregulation." (PMID 24559095, 2014). "Yuan and co-authors reported in 2008 that stable downregulation of YAP1 in breast cancer cell lines resulted in protection of anoikis, promotion of anchorage-independent growth and increased migration and invasion." (PMID 24559095, 2014).
breast cancer (continued). "First, T47D cells have a higher gene and protein expression of YAP1 compared to other luminal breast cancer cell lines such as MCF-7, making the T47D cell line more suitable for YAP1 downregulating experiments." (PMID 24559095, 2014). "We further explored if YAP1 mRNA had different significance in regards to outcome in breast cancer molecular subgroups." (PMID 24559095, 2014). "We set out to clarify the role of YAP1 in breast cancer by examining gene and protein expression in subgroups of patient material and by downregulating YAP1 in vitro and studying its role in response to the widely used anti-estrogen tamoxifen." (PMID 24559095, 2014). "YAP1 depletion resulted in increased tumour growth in nude mice, altogether suggesting a tumour suppressive function of YAP1 in breast cancer." (PMID 24559095, 2014). "Although effects were small, downregulation of YAP1 in a luminal breast cancer cell line resulted in a weaker tamoxifen response as measured by cell viability and activity of the estrogen receptor." (PMID 24559095, 2014). "Since YAP1 protein expression was frequently found to be decreased in breast cancers and rs1820453 A>C may down-regulate the YAP1 expression; we have interesting to know whether this variant is associated with BC risk." (PMID 24223879, 2013). "As an oncogene, the amplification of the YAP1 gene locus at 11q22 is found in several cancer types, including hepatocellular carcinoma, breast cancer, oral squamous cell carcinomas, medulloblastomas, and esophageal squamous cell carcinomas." (PMID 22396793, 2012). "In fact, the LATS1/2 kinases upstream of YAP1 have been shown to be down-regulated in several cancer types including soft tissue sarcoma, astrocytoma, and breast cancer." (PMID 22396793, 2012). "Our findings suggest that YAP1 expression, particularly its subcellular localization, may serve as a promising predictive biomarker in patients with locally advanced breast cancer undergoing neoadjuvant chemotherapy." (PMID 40731926, 2025). "YAP1 is frequently overexpressed in cancers and is known to promote tumorigenesis, but its role is complex and context-dependent, with evidence supporting both oncogenic and tumor-suppressive functions in different breast cancer models." (PMID 41226688, 2025). "Similarly, in breast cancer, YAP1 activation is correlated with increased mammographic density and tissue stiffness, driving tumor initiation and therapy resistance." (PMID 40977060, 2025). "YAP1 is highly expressed and hypomethylated in human breast cancer tissues." (PMID 41294885, 2025). "Similarly, analyses of genomic data from over 2000 breast cancer samples revealed that elevated YAP1 expression predicted significantly poorer 15-year survival, particularly in basal (ER-negative) subtypes." (PMID 40731926, 2025). "Previous studies have shown that basal-type and post-EMT breast cancer cell lines are particularly sensitive to dasatinib, with elevated expression of genes such as moesin (MSN), caveolin-1 (CAV1), and yes-associated protein-1 (YAP1), which are associated with the SRC signaling pathway." (PMID 41462902, 2025). "Further functional studies are warranted to determine whether this shift correlates with reduced oncogenic transcriptional output and whether such changes can be therapeutically exploited in YAP1-expressing breast cancers." (PMID 40731926, 2025). "In this study, we screened our in-house library of small molecule compounds and identified that Abemaciclib, a selective cyclin-dependent kinase 4 and 6 (CDK4/6) inhibitor approved by FDA for breast cancer treatment, as the strongest inhibitor of YAP1 activity." (PMID 40307228, 2025). "Upregulated Yap1 signature was also detected in patient-matched post-chemotherapy breast cancer tissues (accession numbers GSE21974 and GSE4382), suggesting that Yap1 signaling activation is also an adaptive response to chemotherapies in breast cancers, similar to that in PDAC." (PMID 39468013, 2024).
breast cancer (continued). "Additionally, circRNAs have been implicated in cancer genesis and pathogenesis; for instance, hsa:circ_0005273 has been shown to promote breast cancer tumorigenesis by sponging miR-200a-3p to upregulate YAP1, thereby affecting the Hippo pathway." (PMID 39159001, 2024). "Has_circ_0005273 accelerates breast cancer progression via regulating the miR-200a-3p-YAP1-Hippo signaling axis and inactivating the axis, which might be employed as a biomarker and therapeutic target." (PMID 37692482, 2024). "A recent study has shown that high expression of YAP1 is detrimental to ER+ breast cancer." (PMID 39563370, 2024). "Thus, miR-34a and miR-605-5p induce cellular senescence and apoptosis in human breast cancer cells by regulating the YAP1/Hippo pathway." (PMID 39345743, 2024). "Notably, the responses of different breast cancer subtypes to YAP1 upregulation are quite different." (PMID 39563370, 2024). "Notably, we discovered novel miRNAs that target MDM4 and MDM2; this study enhances our understanding of the YAP1/Hippo pathway and the functions of miRNAs as novel therapeutic targets in breast cancer." (PMID 39345743, 2024). "YODA 1 activation in MDA-MB-468 breast cancer cells induced a YAP1 localization reset phenomenon." (PMID 38632473, 2024). "YAP1 is a specific regulator of stem-like properties in basal-like breast cancer cells." (PMID 39563370, 2024). "The modulation of YAP1 activity could help to manage the long-term treatment plan in HR+HER2− breast cancer." (PMID 37894401, 2023). "Interaction of YAP1 and ESR1 in nuclei is a unique feature of HR+HER2− breast cancer, and thus YAP1 could serve as a prognostic marker as well as a therapeutic target in patients with HR+HER2− breast cancer." (PMID 37894401, 2023). "In conclusion, YAP1 acts as a tumor suppressor in HR+HER2− breast cancer." (PMID 37894401, 2023). "Hsa_circ_0005273 could upregulate the expression of YAP1 through miR-200a-3p, thus promoting the progression of breast cancer." (PMID 36849972, 2023). "Based on the positive correlation between YAP1 expression and tumor stiffness in HR+HER2− breast cancer, we further aimed to evaluate whether YAP1 expression correlates with ODX RS." (PMID 37894401, 2023). "In summary, YAP1 could serve as a prognostic marker as well as potential therapeutic target in HR+HER2− breast cancer patients." (PMID 37894401, 2023). "In breast cancer, there have been controversies on the role of YAP1 in tumor biology." (PMID 37894401, 2023). "Interestingly, in breast cancer, the complex between YAP1/TEAD4 can bind to enhancer regions of the estrogen receptor gene, causing an increase in the proliferation of estrogen-responsive breast cells." (PMID 36830634, 2023). "Also, we used human breast tissues and observed significant correlations between YAP1 expression and ODX RS, which confirmed previous in vitro studies, and clarified the role of YAP1 in breast cancer." (PMID 37894401, 2023). "Furthermore, using METABRIC data, we found positive correlations between expression of ZFP36 and genes associated with the stem-like phenotype, as TWIST1, TWIST2, SNAI1, ZEB1, ZEB2, ALDH1A and YAP1 in all breast cancer subtypes." (PMID 38274271, 2023). "YAP1 expression was positively correlated with Notch1 in breast cancer." (PMID 37759462, 2023). "Considering previous studies and our results together, we speculate that YAP1 could be a surrogate marker for prognosis or a therapeutic target in HR+ breast cancer, which should be validated by further research." (PMID 36291755, 2022). "To evaluate whether altered expression of the IL‐18 gene have an effect on YAP1, associated with breast cancer progression and metastasis, we studied the expression of IL‐18, IFNG and YAP1 genes." (PMID 34196131, 2022). "YAP1 has been demonstrated to regulate invadopodia in breast cancer cell lines in vitro." (PMID 35773411, 2022). "Low expression of YAP1 was associated with reduced survival in ER+, but not in ER-, breast cancer patients." (PMID 35217640, 2022).
breast cancer (continued). "Next, we tested whether YAP1 is necessary and sufficient for invadopodia formation in breast cancer cells." (PMID 35773411, 2022). "More recently, breast cancer PDX models that preserve patient intratumoral heterogeneity and clonal architecture have been reported, including endocrine therapy-resistant models that feature ERα Y537 mutations, ESR1 gene amplification, or ESR1/YAP1 fusion." (PMID 36045910, 2022). "YAP1 expression, along with tumor stiffness, may serve as a prognostic candidate in HR+ breast cancer." (PMID 36291755, 2022). "YAP1 promotes cell proliferation and inhibits apoptosis of breast cancer cells." (PMID 35407556, 2022). "Additionally, hsa_circ_0005273 was observed to be upregulated in breast cancer cells and tissues and bind to miR-200a-3p to stimulate YAP1 expression, ultimately inactivating the Hippo pathway." (PMID 35673576, 2022). "Also, IL‐18 can be considered as a potential target for tumor treatment in YAP1 overexpressed breast carcinoma." (PMID 34196131, 2022). "Using The Cancer Genome Atlas (TCGA) database, we analyzed the association between stromal index, EMT, and stemness-related genes across 1084 breast cancer patients, identifying positive correlation between YAP1, EMT, and stemness genes in samples with a high-stromal index." (PMID 34680267, 2021). "But lower YAP1 expression was observed in breast cancer, lung cancer, and esophageal cancer." (PMID 34257617, 2021). "Exosomal miR-92 derived from cancer-associated fibroblasts promotes migration and proliferation of breast cancer cells, miR-92 can promote PD-L1 expression by enhancing occupation between YAP1 and PD-L1 enhancer regions to suppress immune cell function in breast cancer." (PMID 34853307, 2021). "Studies have shown that YAP1 acts as a proto-oncogene in many tumours, including breast cancer." (PMID 34353343, 2021). "Furthermore, the expression level of YAP1 substrates was also downregulated in the HPR-knockdown breast cancer cell lines." (PMID 34462427, 2021). "In addition, YAP1 is a potentially valuable therapeutic target for patients with breast cancer, especially in TNBC." (PMID 33718163, 2021). "According to available TCGA data, GLI1 is related to YAP1 in breast cancer patients." (PMID 34445421, 2021). "Currently, the role of YAP1 in breast cancer remains controversial." (PMID 33718163, 2021). "YAP1 has been confirmed to be overexpressed in a variety of tumors, including gastric tumors, liver tumors, ovarian cancer, and breast cancer, suggesting that YAP1 has a role as a candidate oncogene in tumorigenesis." (PMID 33178690, 2020). "Several studies have shown that YAP1 is an oncogene highly express in numerous cancer types including bladder cancer, breast cancer (Kim, Jung & Koo, 2014), gastric cancer, hepatocellular cancer, nonsmall-cell lung cancer, and CRC that associate with tumor progression and poor prognosis." (PMID 33240680, 2020). "Furthermore, immunohistochemistry analysis of breast cancer tissues showed that YAP1 and JAG1 were differentially expressed in breast cancers with different grades." (PMID 32046779, 2020). "Interestingly, it has been recently reported that TAZ and YAP1 enhance PD-L1 levels in breast-cancer cell lines." (PMID 32365528, 2020). "In breast cancer, YAP1 and TAZ activity increases when cells actively incorporate glucose." (PMID 32678516, 2020). "One report showed that miR-200a promotes breast cancer metastasis by targeting YAP1." (PMID 32414208, 2020).